TMEM244 (transmembrane protein 244)
Synonyms: C6orf191; bA174C7.4
Tractability: Antibody: UniProt predicts a signal peptide or a membrane-spanning region.
Gene: Protein-coding gene on chromosome 6 (129,827,945 to 129,861,547, reverse strand). Ensembl gene ENSG00000203756.
Subcellular location: Membrane
Gene Ontology:
Cellular component: membrane
Genetic constraint (gnomAD): Loss-of-function variants: 8 observed, 6.52 expected, observed/expected ratio (o/e) 1.23, 90% interval 0.7 to 1.87. That is too few expected variants to judge how well the gene tolerates losing a copy. Missense variants: 74 observed, 66.39 expected, observed/expected ratio (o/e) 1.11, 90% interval 0.92 to 1.35. Synonymous variants: 20 observed, 24.55 expected, observed/expected ratio (o/e) 0.81, 90% interval 0.57 to 1.18.
Homologues: Orthologues: chimpanzee TMEM244 (99% identical), macaque TMEM244 (92% identical), rabbit TMEM244 (83% identical), pig TMEM244 (80% identical), zebrafish tmem244 (48% identical), tropical clawed frog TMEM244 (44% identical). Paralogues in human: SYS1 (21% identical).
Diseases named in the same sentence as TMEM244 in open-access papers:
TMEM244 is named in the same sentence as 10 diseases in open-access papers, as found by Europe PMC text mining. Sharing a sentence is not in itself a finding about the gene and the disease. The quoted sentences say what the papers report.
Sézary syndrome (4 papers, 2020 to 2025). "Recently, the expression of the TMEM244 gene was acknowledged to be a diagnostic marker for Sézary syndrome, a rare cutaneous T-cell lymphoma (CTCL)." (PMID 36834942, 2023). "Our current results show that the expression of TMEM244 gene is associated with T‐cell lymphomas, especially with Sézary syndrome, and is a result of specific hypomethylation of its promoter." (PMID 32794659, 2020). "Previous studies have demonstrated that transmembrane protein 244 gene (TMEM244) is ectopically expressed in Sézary syndrome (SS)." (PMID 35831833, 2022). "A significantly higher expression of TMEM244 was identified in Sézary syndrome patients, not only compared to healthy individuals but also to SS clinical mimickers, such as mycosis fungoides and erythrodermic manifestations of non-malignant diseases, therefore indicating its diagnostic potential." (PMID 36834942, 2023). "Since both, TMEM244 expression and its promoter demethylation, are not detected in normal lymphoid cells, they can be potentially used as markers in Sézary syndrome and some other T‐cell lymphomas." (PMID 32794659, 2020).
T-cell lymphoma (2 papers, 2022 to 2023). "Further studies showed that TMEM244 is expressed in T-cell lymphomas as a result of specific hypomethylation of its promoter, and this expression is associated with poor overall survival in T-cell lymphoma patients." (PMID 36834942, 2023).
B‐cell lymphoma (1 paper, 2020). "In this study, TMEM244 expression was quantified in different T‐ and B‐cell lymphoma and leukaemia patients, in mononuclear cells of healthy individuals and in four T‐cell lymphoma (TCL) and one TALL cell lines." (PMID 32794659, 2020).
lymphoma (1 paper, 2020). A malignant (clonal) proliferation of B- lymphocytes or T- lymphocytes which involves the lymph nodes, bone marrow and/or extranodal sites. "Samples with TMEM244 expression, among them mostly SS and a few other T‐cell leukaemia/lymphoma cases, had promoter region hypomethylated, while in all samples not expressing the gene, the promoter was methylated." (PMID 32794659, 2020). "Only trace TMEM244 expression was detected in healthy individuals (C1‐C5 mean ± SD=19E‐6 ± 13E‐6; BM1 16E‐6), while in majority of T‐cell leukaemia/lymphoma cases and CTCL T‐cell lines the expression of TMEM244 was present." (PMID 32794659, 2020).
TMEM244 also shares sentences with these, for which no sentence is quoted: acute lymphoblastic leukemia (1 paper); cancer (1); cutaneous T-cell lymphoma (1); leukaemia (1); mycosis fungoides (1); T-cell acute lymphoblastic leukemia (1).